AGR3 (anterior gradient 3, protein disulphide isomerase family member)
Diseases named in the same sentence as AGR3 in open-access papers (continued):
Sharing a sentence is not in itself a finding about the gene and the disease.
tumor (15 papers, 2003 to 2025). "This association between AGR3 mRNA expression and the tumour grades G1 and G2 was further corroborated performing Fisher’s exact test (P < 0.01)." (PMID 25875093, 2015). "The authors13warned that AGR3 can promote tumor progression, through processes of proliferation, invasion, and resistance to chemotherapy." (PMID 37944928, 2023). "Gene and pathway enrichment analysis revealed that the ‘Tumor_2’ population upregulates fucosylation, hydroxylation and HIF pathways, and genes associated with the basal-like tumor subtype (BTNL8, AGR3 and LYZ)." (PMID 35995947, 2022). "Since AGR2 and AGR3 expressions were highly correlated in all the TCGA tumour types studied as well as in the CCLE collection, we focused our interest on AGR2 and simply indicated original features concerning AGR3." (PMID 35857928, 2022). "In the collections of cell lines of GDSC and CCLE, 10 tumour cell lines bear a variation in AGR3 coding sequence, among which five are common to the two databases." (PMID 35857928, 2022). "In order to distinguish germline polymorphisms from potential mutations in tumour tissues, we first listed the AGR2 and AGR3 gene polymorphisms identified in the NCBI dbSNP database." (PMID 35857928, 2022). "In the TCGA, we also identified the genes that were co-expressed with AGR2 or AGR3 in five major tumour types (COADREAD, BRCA, LUAD, LUSC and OVCA)." (PMID 35857928, 2022). "In conclusion, the role of AGR3 as a tumour signalling molecule in EOC is poorly understood and requires further investigation." (PMID 34452625, 2021). "The common downregulated genes in metastasis and primary tumor include anterior gradient protein 3 homolog (AGR3) and Sentan cilia apical structure protein (SNTN)." (PMID 31600962, 2019). "Expression of PDI, PDIA6, PDIR, ERp57, ERP72 and AGR3 is significantly correlated with patients’ tumor stages (stage I, stage II, stage III, stage IV, p = <0.001)." (PMID 29262583, 2017). "Statistically quantifying AGR3 protein expression we observed a significant over-expression (P < 0.05) of AGR3 in tumour samples compared with normal breast tissues." (PMID 25875093, 2015). "Univariate analysis demonstrated that patients with low and intermediate grade tumours showing high AGR3 protein expression had a significantly reduced tumour-specific survival compared to those with low AGR3 expression." (PMID 25875093, 2015). "Xenium identified AGR3 as a tumor epithelial marker associated with DCIS ROIs, but not the invasive ROI." (PMID 38114474, 2023). "AGR3’s role as a component of tumour signalling pathway remains poorly understood." (PMID 34452625, 2021). "As a consequence, expression regulation of both AGR2 and AGR3 in EOC could determine tumour evolution in a way that would promote its growth and aggressiveness." (PMID 34452625, 2021). "AGR3 was chosen because it is poorly understood as a tumor-signaling molecule." (PMID 29262583, 2017). "Interestingly, AGR2 and AGR3 have both been shown to interact with the protein C4.4A (LYPD3), a factor implicated in tumour progression." (PMID 25875093, 2015). "Indeed, concomitant or opposed of AGR2 and AGR3 expression in EOC could determine tumour evolution in a way that would promote its growth and aggressiveness, thus associating the differential expression of AGR2 and AGR3 to tumour outcomes." (PMID 34452625, 2021). "Besides, under the microenvironment stresses and DNA damage, anterior gradient protein 3 (AGR3) can promote the survival of tumor cells and may participate in the coordination of cell proliferation, survival, and metastasis." (PMID 31217907, 2019). "Patients with low and intermediate grade tumours showing high AGR3 expression had an unfavourable outcome (mean tumour-specific survival: 142.5 months ± 9.6; 95% CI: 123.8–161.2) compared to those with low AGR3 expression (mean tumour-specific survival: 181.7 months ± 10.1; 95% CI: 162.0–201.4)." (PMID 25875093, 2015).
tumor (continued). "Here, the tumor cells elevate expression of immune signaling MHC II molecules (CD74, HLA-DRB1, HLA-DPA1) and immune-regulating secretory proteins (REG4, AGR2, AGR3), with AGR2 and REG4 specifically upregulated in RCRC." (PMID 41450739, 2025). "AGR3 expression patterns in serous and clear cell EOC tissues showed that AGR3 was highly expressed in serous EOC and in clear cell EOC in tumour versus adjacent tissues." (PMID 34452625, 2021). "In this study, we focused on six PDI family proteins: PDIA6, PDIR, ERp57, ERp72, AGR3 and PDI, because these proteins have been found to promote tumor cell proliferation or have unknown cellular functions." (PMID 29262583, 2017). "After subgrouping our cohort, we found that AGR3 has a significant (P < 0.05) prognostic impact in the low (G1) and intermediate (G2) grade tumours, but not in the group of high grade (G3) cases." (PMID 25875093, 2015). "In concordance with our AGR3 mRNA data abundant AGR3 protein expression was found in tumours of luminal subtype whereas only weak or absent AGR3 protein staining was observed in TNBC tumours." (PMID 25875093, 2015). "However, the non-genetic gain-of-function alterations, acquired by overexpression and non-canonical localizations of AGR2 and AGR3 proteins, may be pivotal for tumour development and progression." (PMID 35857928, 2022). "To validate whether the significance of the relationship between AGR3 expression and patient survival is independent of other tumour variables, we performed Cox’s multivariate analysis including only those variables that showed significance in univariate analysis." (PMID 25875093, 2015).
adenocarcinoma (2 papers, 2021 to 2022). A common cancer characterized by the presence of malignant glandular cells. "The AGR2 and AGR3 genes have been shown by numerous groups to be functionally associated with adenocarcinoma progression and metastasis." (PMID 35857928, 2022). "AGR2 and AGR3 genes are localized on chromosome 7, side by side (7p21.1), and their protein products are both overexpressed and their localizations deregulated in many types of adenocarcinomas." (PMID 35857928, 2022). "The discovery of the anterior gradient proteins AGR2 and AGR3, which are highly related members belonging to the protein disulfide isomerase (PDI) family, attracted researchers’ attention due to their putative involvement in adenocarcinoma development." (PMID 34452625, 2021).
bacterial infection (1 paper, 2021). "Loss of AGR3 might promote viral and bacterial infection and induce immune inflammation to increase COPD exacerbation." (PMID 34177583, 2021).
neurodevelopmental disorder (1 paper, 2020). A behavioral and cognitive disorder with onset during the developmental period that involves impaired or aberrant development of intellectual, motor, or social functions. "Two other genes (AGR3, MTMR3) have not been previously associated with ASD or neurodevelopmental disorders." (PMID 32820185, 2020).
AGR3 also shares sentences with these, for which no sentence is quoted: lung carcinoma (2 papers); benign tumors (1); bladder carcinomas (1); deafness (1); glioma (1); invasive ductal carcinoma (1); metastatic cancer (1); mucinous tumours (1); ovarian adenocarcinoma (1); prostate (1); skin cutaneous melanomas (1); triple-negative breast carcinoma (1).